AGRP (agouti related neuropeptide)
Diseases named in the same sentence as AGRP in open-access papers (continued):
Sharing a sentence is not in itself a finding about the gene and the disease.
colitis (1 paper, 2023). Inflammation of the colon. "It is worth mentioning that AgRP neurons were involved in stress induced colitis susceptibility rather than spontaneous colitis, implying that the pathology of colitis required conditions of DSS stimulation." (PMID 36641530, 2023).
dementia (1 paper, 2023). Loss of intellectual abilities interfering with an individual's social and occupational functions. "We identified a high expression level of AGRP and NTproBNP in the plasma of patients with dementia; a SOMAmer-based study also reported the association of these proteins with a high risk of dementia." (PMID 37175824, 2023).
dwarfism (1 paper, 2018). "Dlx1/2-deficient mice show a loss-of-GHRH-neurons and an increase of AgRP-neurons, and consistently develop dwarfism and consume less energy." (PMID 29795232, 2018).
endometrial cancer (1 paper, 2011). Primary or metastatic malignant neoplasm involving the endometrium (mucous membrane that lines the endometrial cavity). "In this study, we determined whether the disease-free endometrial cancer survivors present with different plasma AgRP levels than controls and whether there was an association with the duration of the disease-free interval." (PMID 29147253, 2011). "In the presented study, we investigated plasma AgRP levels in a sample of 53 endometrial cancer survivors and compared them to 93 controls of similar age, BMI and various menopausal status." (PMID 29147253, 2011). "We demonstrated significant differences in AgRP plasma levels between obese and non-obese endometrial cancer survivors as well as across the whole cohort of endometrial cancer survivors and the controls, whereas this association was age-independent." (PMID 29147253, 2011).
Failure to thrive (1 paper, 2025). Failure to thrive (FTT) refers to a child whose physical growth is substantially below the norm. "In a transgenic mouse model of PWS, which displayed failure to thrive during the neonatal period, the expression of AgRP mRNA was decreased while the mRNA expression of POMC was upregulated in PWS-mice neonates." (PMID 40136445, 2025). "Since AgRP stimulates appetite and the POMC-derived peptide, α-MSH, stimulates satiety, these changes together will decrease feeding and may thus contribute to the failure to thrive in PWS neonatal mice." (PMID 40136445, 2025).
folate deficiency (1 paper, 2019). A nutritional condition produced by a deficiency of FOLIC ACID in the diet. "Specifically, folate deficiency led to decreased NPY expression and to overexpression of AgRP mRNA, along with reduced expression of the leptin and insulin receptors, whereas ghrelin overexpression was associated with reduced expression of these receptors." (PMID 31615150, 2019).
heart failure (1 paper, 2025). Inability of the heart to pump blood at an adequate rate to meet tissue metabolic requirements. "Since we found AgRP in the human CB, it is tempting to speculate that AgRP at the level of the CB may play a role in adaptations to chronic hypoxia resulting from sleep apnea, heart failure, respiratory infections, and other hypoxic conditions with subclinical symptoms in humans." (PMID 39793758, 2025).
hepatoma (1 paper, 2011). "We thus identified SPARC, PLG, G6PC, NR1D2 and AGRP as RORα targets in hepatoma cells." (PMID 21818335, 2011).
hyperthyroidism (1 paper, 2012). Overactivity of the thyroid gland resulting in overproduction of thyroid hormone and increased metabolic rate. "In keeping with these data, we have recently reported that thyroid hormone-induced feeding, both short-term (central administration) and long-term (hyperthyroidism), is mediated by selective modulation of the mTOR pathway in the ARC, which elicits increased expression of AgRP and NPY." (PMID 23056530, 2012).
hypothyroidism (1 paper, 2024). Abnormally low levels of thyroid hormone. "Single-cell sequencing of ARC neurons revealed that Thra and Thrb are expressed in AgRP and POMC neurons, and that their expression levels are similar in both physiological states, suggesting that hypothyroidism in IBA animals is not caused by receptor downregulation." (PMID 38987241, 2024).
Infertility (1 paper, 2018). "A seminal study by Padilla and colleagues indicated that AgRP-expressing neurons are activated during starvation and are involved in leptin-associated infertility during negative energy state." (PMID 29755406, 2018).
lipodystrophy (1 paper, 2022). A congenital or acquired disorder characterized by abnormal loss or redistribution of the adipose tissue in the body. "The effects on adipokines, ghrelin, and AgRP may also be important to producing IR in the face of low AT storage, as well as promoting AT mass regain along with reductions in IR during the lipodystrophy recovery." (PMID 36176462, 2022).
malocclusion (1 paper, 2023). "The NOR indices were lower and the agouti-related peptide (AgRP) mRNA levels and number of c-Fos-positive cells were higher in the malocclusion/powder group than in the other groups." (PMID 37168929, 2023).
mood disorder (1 paper, 2023). A cognitive disorder a disturbance in which the person's mood is hypothesized to be the main underlying feature. "High-fat diet-mediated desensitization reduces GABAergic output from AgRP neurons to downstream melanocortin four receptors in the dorsal striatal terminal dorsal bed nucleus neurons, leading to severe mood disorders." (PMID 38298928, 2023).
morbid obesity (1 paper, 2012). An excess of body weight, normally defined as an individual with a body mass index greater than 35 or a body weight greater than one hundred percent of ideal body weight. "Although disruption of the STAT3 binding site in LepRb or deletion of neuronal STAT3 results in severe hyperphagia and morbid obesity, deletion of STAT3 in either POMC or AgRP neurons only slightly increases food intake and adiposity in mice." (PMID 22291999, 2012).
neuroendocrine tumor (1 paper, 2020). "Therefore, AgRP has been suggested as a potential neuroendocrine tumor diagnostic marker." (PMID 33266265, 2020).
ovarian teratoma (1 paper, 2021). A non-seminomatous germ cell tumor arising from the ovary. "From this, it can be speculated that the ligand of MC4R in the development of ovarian teratomas in this double-gene-modified line is AGRP." (PMID 33568756, 2021).
pancreatic cancer (1 paper, 2021). "To address this hypothesis, we examined whether intracerebroventricular (ICV) infusion of agouti-related peptide (AgRP), an inverse agonist of the MC4R, improved appetite during the progression of pancreatic cancer cachexia." (PMID 33824339, 2021).
Polydipsia (1 paper, 2023). Excessive thirst manifested by excessive fluid intake. "Strikingly, both male and female Cpt1aKO mice showed polydipsia and polyuria, with more reduced serum vasopressin levels in females and without osmolality alterations, indicating a direct involvement of Cpt1a in AgRP neurons in fluid balance." (PMID 36966335, 2023).
pulmonary fibrosis (1 paper, 2023). Chronic progressive interstitial lung disorder characterized by the replacement of the lung tissue by connective tissue, leading to progressive dyspnea, respiratory failure, or right heart failure. "Currently, there is a lack of research examining the role of AGRP in the context of pulmonary fibrosis." (PMID 38274787, 2023).
steatosis (1 paper, 2021). Increased lipid within the cytoplasm of cells. "This reduction in steatosis could be mediated, at least in part, by reduced AgRP neuron activity signalling to peripheral tissues." (PMID 34215821, 2021).
stress-related disorder (1 paper, 2021). Stress-related disorders are mental health disorders that are a result of an atypical response to both short and long-term anxiety due to physical, mental, or emotional stress. "Another candidate downstream target of AgRP neurons is the bed nucleus of the stria terminalis (BNST), which has emerged as a key player in stress-related disorders." (PMID 33432188, 2021).
cancer (9 papers, 2008 to 2021). A tumor composed of atypical neoplastic, often pleomorphic cells that invade other tissues. "CGRP neurons are activated by upstream circuits that respond to cancer-associated signals, and are inhibited by those that promote feeding, including hypothalamic AgRP/neuropeptide Y neurons." (PMID 31773065, 2019). "How cancer-induced changes in glucose concentrations and other orexigenic hormones disrupts AgRP neural activity remains to be determined." (PMID 32193527, 2020). "Genetic ablation of these neurons, or activation of upstream AgRP neurons, can counteract cancer-induced anorexia." (PMID 32193527, 2020). "For example, cancer-induced elevations in circulating lactate can influence the activity of neurons involved in energy balance and food intake, including agouti-related protein (AgRP) neurons in the arcuate nucleus of the hypothalamus." (PMID 31174326, 2019). "Further work is needed to examine pre-synaptic partners of these neurons (including the hunger-inducing AgRP neurons in the arcuate nucleus), and how they become deregulated in the context of cancer and/or cancer treatment." (PMID 31174326, 2019). "Cancer-induced changes in energy balance offer an opportunity to modulate relevant neural circuits (e.g., AgRP, POMC, HO) to not only improve quality of life, but reduce energy availability to the tumor." (PMID 31174326, 2019). "Taken together, these results demonstrate the ability of aGRP in dealing with complex expression patterns for cancer biomarker identification." (PMID 30390627, 2018). "A series of experiments demonstrated that cancer cachexia is ameliorated by central MC4R blockade in MC4R knock out mice or by peripheral administration of an antagonist (e.g. agouti-related protein – AGRP) in rats, mice and sheep." (PMID 18377640, 2008). "As cancer drastically alters energy balance, influencing the activity of specific brain nuclei regulating metabolism and food intake (e.g., hypocretin, AgRP, POMC, CGRP neurons) represents a strategy to not only improve quality of life, but limit energy availability to the cancer." (PMID 31773065, 2019). "It is possible that the increased circulating AgRP levels might stimulate feeding behavior and inhibit pro-cachechtic pathways, thus making our cancer survivors less prone to cachexia-related complications." (PMID 29147253, 2011). "(ii) Alternatively, in the presence of cancer certain factors/conditions might alter the receptor, so that binding properties for an antagonist (e.g. AGRP) might improve." (PMID 18377640, 2008). "Both aGRP and GRP are a regulation-based statistic for cancer biomarker identification, whose absolute values and signs indicate the strength and direction of regulation respectively." (PMID 30390627, 2018). "The AgRP plasma levels were significantly higher in the cases than in the controls; AgRP levels were the lowest in obese control women (77.4 ± 19.8 pg/ml); on the contrary, the AgRP plasma levels were highest in non-obese cancer survivors (100.5 ± 21.12 pg/ml)." (PMID 29147253, 2011). "In addition, among the 3686 negative aGRP DEGs, hormone receptor PGRMC2 (aGRP = − 0.635) was previously reported to be a tumor suppressor and an inhibitor of migration of cancer cell." (PMID 30390627, 2018).
metabolic disorders (9 papers, 2021 to 2025). "These developmental windows represent important periods of vulnerability during which perturbations in the perinatal environment may lead to abnormal POMC and AgRP neuron development, causing lifelong metabolic diseases." (PMID 35474338, 2022). "The excess ROS promotes the nuclear translocation of FoxO1, which in turn upregulates AgRP expression, ultimately resulting in metabolic disorders." (PMID 41037185, 2025). "Proteomic analysis illustrated that the expression of certain proteins including AGRP, LEP and SORT1 associated with metabolic diseases decreased following THD treatment." (PMID 40242450, 2025). "IL-6 can suppress synaptic plasticity in hypothalamic arcuate nucleus neurons, reduce the activity of POMC neurons (appetite suppression), and promote the activation of AgRP neurons (appetite promotion), leading to metabolic disorders." (PMID 41294833, 2025). "In metabolic diseases like obesity, microglial dysfunction disrupts the inhibitory/excitatory balance of AgRP-pancreatic neural projections, leading to abnormal insulin secretion—an effect that complements the metabolic dysregulation caused by HPA axis dysfunction." (PMID 41294833, 2025).
tumor (7 papers, 2011 to 2022). "We previously used yeast-surface display and high-throughput library screening to identify knottin variants, based on EETI and AgRP, that possess high affinity and specificity for integrin receptors expressed on tumor cells and their neovasculature." (PMID 23573262, 2013). "Using a rational approach, we grafted the integrin-binding loop from an engineered AgRP mutant into an AgTx scaffold, resulting in an AgTx variant that bound to tumor cells with low nanomolar affinity." (PMID 23573262, 2013). "Similar to Lcn2-KO tumor-bearing mice, AgRP-treated mice demonstrated a significant improvement in food intake and modest improvements in muscle mass." (PMID 33824339, 2021). "Similar to the Lcn2-KO tumor-bearing mice, AgRP-treated mice had improved skeletal and cardiac tissue mass at the end of the study." (PMID 33824339, 2021). "In these studies, engineered EETI and AgRP knottins exhibited rapid tumor localization and blood clearance via the kidneys, resulting in robust tumor contrast compared to the surrounding tissue." (PMID 23573262, 2013). "In addition, resistance to the hormones Neuropeptide Y (NPY) and Agouti-related protein (AgRP), which promote food intake, has also been observed in tumor-bearing animals." (PMID 35455957, 2022). "Consistent with Lcn2-KO tumor-bearing mice, ICV AgRP treatment did not alter ubiquitin-ligase or autophagy-related catabolic pathways in skeletal muscle or cardiac tissue, suggesting that improved caloric intake improves muscle mass through alternative pathways during cachexia." (PMID 33824339, 2021).
infection (5 papers, 2010 to 2019). The state of being infected such as from the introduction of a foreign agent such as serum, vaccine, antigenic substance or organism. "The levels of the Rora, SPARC, PLG, G6PC, NR1D2 and AGRP mRNAs were measured by qRT-PCR 24 h, 48 h and 72 h after infection of HepG2 cells with either Ad-RORα or control Ad-GFP." (PMID 21818335, 2011). "Three days after infection the primary cortical neurons were stained for AgRP." (PMID 20701764, 2010). "After infection with DREADD hM3Dq or hM4Di, food intake results were used as an indication of CNO-induced AgRP or POMC neuronal activity, which were similar to findings reported earlier." (PMID 31506541, 2019). "The current study did not directly measure neuronal activity of AgRP or POMC neurons after infection with the DREADD virus, which is a limitation of this investigation." (PMID 31506541, 2019). "However, the infection of POMC neurons or AgRP neurons in the ARC did not produce any transsynaptic labeling in the NTS." (PMID 25870542, 2015).
neurodegenerative disease (1 paper, 2017). A disorder of the central nervous system characterized by gradual and progressive loss of neural tissue and neurologic function. "We assessed the therapeutic applications of WJ-MSCs and AgRP in neurodegenerative diseases by delivering either WJ-MSCs or AgRP directly into the left hippocampus of 10 to 13-month(mo)-old 5XFAD transgenic AD mice." (PMID 28051110, 2017). "Collectively, these findings suggest strong therapeutic potential for WJ-MSCs and AgRP to enhance proteasome activity, thereby potentially reducing abnormal protein aggregation and delaying the clinical progression of various neurodegenerative diseases." (PMID 28051110, 2017).
AGRP also shares sentences with these, for which no sentence is quoted: type 2 diabetes (6 papers); eating disorder (4); mental disorder (2); atherosclerosis (1); bipolar disorder (1); breast carcinoma (1); cardiovascular diseases (1); Central hypothyroidism (1); Cushing syndrome (1); gastric cancer (1); glioblastoma (1); Huntington disease (1); Hyperphagia (1); hyperprolactinemia (1); hyperuricemia (1); hypogonadotropic hypogonadism (1); Lewis lung carcinoma (1); neuroblastoma (1); obesity syndromes (1); opioid dependence (1); parasitic infection (1); POMC deficiency (1); proteinopathies (1); psoriasis (1); respiratory infections (1); Sleep apnea (1); sleep disorder (1); syndromic (1); uremia (1).